MIR7-3HG (MIR7-3 host gene)
Synonyms: C19orf30; LINC00306; NCRNA00306; PGSF1; PGSF1a; PGSF1b; Huh7; uc002mbe.2
Gene: Long non-coding RNA gene on chromosome 19 (4,769,031 to 4,785,077, forward strand). Ensembl gene ENSG00000176840.
Diseases named in the same sentence as MIR7-3HG in open-access papers:
MIR7-3HG is named in the same sentence as 7 diseases in open-access papers, as found by Europe PMC text mining. Sharing a sentence is not in itself a finding about the gene and the disease.
MIR7-3HG shares sentences with these, for which no sentence is quoted: tumor (7 papers); hepatocellular carcinoma (6); liver cancer (3); hypophysitis (2); glioma (1); hypopituitarism (1); viral hepatitis (1).